STAT3 (signal transducer and activator of transcription 3)
Diseases named in the same sentence as STAT3 in open-access papers (continued):
Sharing a sentence is not in itself a finding about the gene and the disease.
tumor (continued). "Similarly, in a mouse model of PDAC, the number of bone marrow-derived MSCs significantly increased following gemcitabine treatment in the tumor stroma, and the gemcitabine-educated MSCs have a positive regulatory effect on CSCs through the STAT-3–CXCL-10–CXCR-3 paracrine signaling axis." (PMID 31108941, 2019). "Thus, therapeutic approaches targeting the JAK/STAT3 pathway may benefit cancer patients, not only through promoting tumor inhibition but also by attenuating PD-L1 expression to enhance anti-tumor immunity." (PMID 31511071, 2019). "In addition, further key cardiac signalling pathways were affected by B16F10 tumour burden including constitutive high activation of signal transducer and activator of transcription 3 (STAT3), and reduction of mitogen-activated protein kinase p38 (p38) and mitogen-activated protein kinase p44/42." (PMID 31667271, 2019). "Therefore, additional studies will be needed to define whether single ligand-receptor inhibitors can sufficiently impact STAT3 activation, thus suppressing tumor growth." (PMID 31684144, 2019). "Therefore, we hypothesised that the presence of tumour cells impaired the function of the mTOR pathway, which paralleled the effects attributed to increased phosphor-STAT3 levels in muscle cells." (PMID 30975087, 2019). "In addition, WA has been reported to inhibit STAT3 and promote tumor cell death." (PMID 31319622, 2019). "However, it should also be noted that in some cancers STAT3 has tumor suppressive activities." (PMID 31752278, 2019). "We next ascertained that the striking anti‐tumor effect of bazedoxifene treatment also extended to the epithelium of the small intestine, which is also susceptible to the therapeutic benefit conferred by inhibition of the IL11/STAT3 signaling axis at the level of the gp130‐associated JAK1/2 kinases." (PMID 30885958, 2019). "Thus, excessive leptin signaling might be involved in neoplasia and metaplasia in the stomach, mediated by the STAT3-HIF-1-Hes-1 axis." (PMID 31141984, 2019). "Furthermore, it was investigated whether the reduction in tumor progression by silencing Stat3 expression could affect the tumor immune profile." (PMID 31581535, 2019). "Therefore, we focused on the regulation of miRNAs on tumor MDSC through JAK/STAT3 further." (PMID 31413755, 2019). "TAMs make a huge contribution to tumor development by modulating angiogenesis, ECM remolding, chronic inflammation and immune suppression processes via complex interaction between signaling pathways of NF‐κB, Jak‐STAT3, chemokine‐receptor interaction and TGF‐β associated." (PMID 31222971, 2019). "Furthermore, STAT3 phosphorylation was also decreased in the GMPs of CXCR2-/- tumor-bearing mice." (PMID 31395859, 2019). "Thus, the STAT3 signaling pathway may represent a viable mechanistic pathway for diminishing immune cell recruitment into tumor sites, and based on the currently available data, it may interfere with T cell recruitment." (PMID 31775797, 2019). "Also, resveratrol significantly decreased STAT3 activation in cancer cells and tumor growth." (PMID 30791624, 2019). "Also, the STAT3/p-STAT3 expression level in tumor tissue could indicate the deteriorating condition, meaning that STAT3/p-STAT3 could be an important target for various cancers." (PMID 31375715, 2019). "Indeed, although STAT3 expression is detected in PTCs, the majority of the studies reported an increased activity in normal tissues compared to cancer lesions and an inverse correlation between STAT3 expression and tumor size." (PMID 31200515, 2019). "Furthermore, the authors found that STAT3 affects tumour permeability and drug sensitivity in MCS." (PMID 30679726, 2019).
tumor (continued). "Alginate sulfate (AlgS) with STAT3 siRNA were co-assembled and then followed by bioconjugation of N-acetylgalactosamine (GalNAc) which is specific to the asialoglycoprotein receptors that are overly expressed on hepatocytes to produce a novel tumor specific delivery vector (GalNAc-NPs)." (PMID 30847297, 2019). "However, other studies indicate a dual role of STAT3, where it can act as a tumor suppressor." (PMID 31297057, 2019). "In addition, overexpression of STAT3 pY705 and/or pS727 in tumoral tissues has been found to be correlated with poor prognosis and clinicopathological features including larger tumor size, vascular invasion, advanced disease stage and cirrhosis in HCC patients." (PMID 31731457, 2019). "As a ubiquitously-expressed transcription factor, STAT3 has commonly been considered an “undruggable” target for therapy; thus, much research has focused on targeting upstream pathways to reduce the expression or phosphorylation/activation of STAT3 in tumor cells." (PMID 31671769, 2019). "STAT3-mediated release of various cytokines and chemokines can interact and influence components of the tumor microenvironment (TME) and especially immune cell accumulation including T-cells, Natural Killer (NK) cells as well as tumor-associated macrophages (TAMs)." (PMID 31581535, 2019). "Elevated STAT3 activity promotes epithelial-mesenchymal transition (EMT) and a stem cell program in cancer cells, while also suppressing the function of immune cells within the tumor, all of which are important steps that underlie metastasis and therapy failure." (PMID 31684144, 2019). "Hence, providing STAT3 modulation in macrophages is of interest in improving anti-tumor immunity." (PMID 31569687, 2019). "Biomarkers that may guide treatment decisions include the tumor cell‐intrinsic expression of a functional IL‐6 receptor and the constitutive phosphorylation of the downstream transcription factor STAT3, which can be assessed by routine flow cytometric or immunohistochemical testing." (PMID 31515941, 2019). "However, whether SOCS1 and JAK2/STAT3 pathway participate in the proangiogenic switch of CAFs and whether tumor-secreted exosomal miRNAs regulate both regulators are unclear." (PMID 30285793, 2018). "Thus, it is plausible and likely that the tumor stroma and immune microenvironment still contains Stat3 which may be functionally targeted by IL-6 blockade." (PMID 30389925, 2018). "The observation that Sp17+ cells are required to initiate tumor formation in the ID8 model suggests that STAT3 and PD-L1 expression may be key to this process, and that Sp17 may act as a surrogate marker for the presence of these immunosuppressive, metastatic cells in tumors." (PMID 30127274, 2018). "This may allow a tumor-cell- and tissue-specific targeting of STAT3 while sparing healthy cells." (PMID 29914167, 2018). "The STAT3 signaling pathway plays an important role in normal development, particularly hematopoiesis, and regulates cancer metastasis by regulating the expression of genes that are critical to cell survival, cell proliferation, invasion, angiogenesis, and tumor immune evasion." (PMID 30031388, 2018). "Moreover, PRP reduced Foxp3 and Stat3 expression in peritoneal cells from H22 tumor-bearing mice." (PMID 29735884, 2018). "In addition, STAT3 possesses a dual role as tumor suppressor and oncogene." (PMID 30279347, 2018). "The effect of the drug on modulation of STAT3 phosphorylation may also be linked with the inhibition of upstream proteins such as JAK1/2 and c-Src, as we noticed that it can substantially reduce the constitutive activation of these kinases in tumor cells." (PMID 30413072, 2018). "Therefore, STAT3 provides an exceptional molecular target at the key node of the immune system network, based on the antigen-presenting potential of DCs/macrophages or complex tumor-promoting activity of TAMs and MDSCs." (PMID 29921770, 2018).
tumor (continued). "Moreover, CAFs recruit regulatory dendritic cells and facilitate their acquisition of a tolerogenic phenotype through interleukin (IL)-6-mediated signal transducer and activator of transcription 3 (STAT3) activation along with upregulation of Treg via secretion of TGF-β in tumor microenvironments." (PMID 30477236, 2018). "Therefore, STAT3 protein modulation may be an important aspect of the anti-tumor activity of osthole." (PMID 30577812, 2018). "Micro-146a, an important downregulator of immune activity, exerts a negative effect on tumor development in HCC cells by promoting the expression of STAT3 activation-associated cytokines, like TGF-β, IL-17, VEGF, and I IFN, leading to HCC-induced NK cell dysfunction." (PMID 29951542, 2018). "Moreover, mounting evidence have demonstrated STAT3-targeted therapy could effectively inhibit tumor development in various human cancers." (PMID 29423040, 2018). "Interestingly, administration of the natural napthoquinone compound shikonin has been demonstrated to reduce the in vivo growth of tumours that are derived from implantation of 4T1 cells, and this is suggested to be through modulation of STAT3 and Oct3/4 expression." (PMID 29875329, 2018). "STAT3 has also been found to regulate anti-apoptotic functions that can contribute to drug resistance in tumor cells and it was found that OP-D attenuated the expression of various growth regulatory and cell survival proteins that may contribute to its anti-cancer effects." (PMID 30413072, 2018). "Inhibition of the signal transducer and activator of transcription 3 (STAT3) pathway within tumor cells has shown improved outcomes in mouse models specifically, with one study using the siRNA-based method to activate these cells within the tumor microenvironment and subsequently slow tumor growth." (PMID 30701185, 2018). "Interestingly, Treg frequency gets lower in mice with STAT3-blocked HCC cells, indicating that STAT3 activation in tumor cells may be critical in Treg induction and NK cell suppression." (PMID 30463262, 2018). "Moreover, S1PR1 was shown to be closely associated with persistent activation of signal transducer and activator of transcription-3 (STAT3) and IL-6 expression in both tumor cells and the tumor microenvironment, both of which contributed to tumor malignant progression and distant dissemination." (PMID 30242145, 2018). "Therefore, p-STAT3 may be an effective target for inhibiting angiogenesis by reducing the expression of VEGF in the tumor." (PMID 30271456, 2018). "Indeed, we and others have demonstrated that blocking one receptor is not sufficient in inhibiting STAT3 activity, as other uninhibited pathways such as those driven by EGFR, IL-6R and IL-11R can reactivate STAT3, leading to continued tumor growth and refractory outcomes clinically." (PMID 30572654, 2018). "Therefore, we sought to block the STAT3 signaling pathway independently or in combination with conventional chemotherapy as a potential treatment strategy in tumors showing high levels of IL-6 in the tumor microenvironment." (PMID 29930760, 2018). "Similarly, STAT3 also has key roles in inflammation and malignant transformation, where the persistent activation of STAT3 is found to mediate tumor-promoting inflammation, as it can promote pro-oncogenic and inflammatory pathways, including NF-κB and interleukin-stimulated JAK pathways." (PMID 30341316, 2018). "Simultaneous blocking of mTORC1, STAT3 and AKT might be the underlying molecular mechanism for proliferation inhibition, induction of autophagy and caspase-independent cell death all observed in co-treated tumors, which in concert resulted in tumor shrinkage." (PMID 29755689, 2018). "Inhibition of the activation of STAT3, e.g. by the anti-IL6R monoclonal antibody Tocilizumab, is known to down-regulate the immune suppression caused by tumor cells, and inhibition of IL-6 signaling may be a therapeutic for patients with cancer when IL-6 is over-expressed." (PMID 30038723, 2018).
tumor (continued). "However, robust recurrent tumor growth with enhanced JAK2/STAT3 activation and CSC-like phenotype was observed in all mice groups after termination of treatments, but was delayed significantly in the paclitaxel and momelotinib treated group compared to other treatment groups." (PMID 29682172, 2018). "Thus, m-Tyr impact on autophagy may be in part due to STAT3 downmodulation and in turn blocking this pathway may impair tumor growth and progression." (PMID 29396431, 2018). "However, whether the tumour inhibitory effect of MSCs is mediated by the Stat3 signaling pathway is unclear." (PMID 30297887, 2018). "In this patient, we hypothesize that combination of multiple activating mutations and loss of tumor suppressors contributed to tumor progression through over-activation of the JAK-STAT pathway; and was effectively suppressed through direct targeting of STAT3." (PMID 30446007, 2018). "However, genetic background of tumor could modulate the therapeutic response, suggesting that the strategy to enhance tumor radiosensitivity by STAT3 inhibition could be applied to STAT3-dependant GBMs, especially these of the mesenchymal subtype." (PMID 29423098, 2018). "Hence, STAT3 may enhance cancer cell survival by augmenting the adaptation of the cells to the acidic tumor environment and increased acid production." (PMID 30127373, 2018). "Furthermore, N64-sh cells activated STAT3 and Erk1/2 in tumor xenografts." (PMID 30410668, 2018). "On the basis of these results, it could be conceivable to hypothesize STAT3 as a new valid cellular target to develop therapeutic strategies based on the inhibition of STAT3-mediated pathways, in addition to conventional chemotherapy, to deal with tumours in patients exposed to POPs (i.e., β-HCH)." (PMID 30036966, 2018). "Further molecular study has shown that pterostilbene effectively suppressed phosphorylation of STAT3, as well as STAT3 downstream genes that regulate cell cycle and apoptosis, indicating that inhibition of STAT3 pathway may be involved in its anti-tumor activity." (PMID 29986501, 2018). "Furthermore, the pSTAT3-positive subset may have robust STAT3-driven survival signaling of tumor cells that can override the effect of PD-L1-mediated immune evasion." (PMID 30458835, 2018). "Because STAT3 mediates distinct biological effects by interacting with specific cooperating proteins, another strategy to inhibit oncogenic STAT3 functions might be the identification of tumor-specific STAT3 critical cofactors." (PMID 29914167, 2018). "Considering that these genes are well known to favor cancer cell proliferation and anti-apoptosis, our data suggest that YSY01A may exhibit anti-tumor effect via modulating STAT3 signaling, thereby leading to transcriptional down-regulation of STAT3 downstream genes." (PMID 28883791, 2017). "Since ponatinib targets several tyrosine kinases and only FGFR1-activated PI3K/AKT/mTOR and JAK/STAT3 signaling pathways have been investigated in this paper, it is highly likely that the inhibition of other targets also contributed to ponatinib-induced anti-tumor effect in NB." (PMID 27564113, 2017). "Furthermore, tumor-infiltrated MDSCs, which showed the activation of STAT3 signaling, can enhance the stemness of pancreatic cancer cells through the induction of EMT, with a concomitant increase in the expression of stemness genes, including Snail, Slug, ZEB1, NANOG, and OCT-4." (PMID 28337221, 2017). "In addition, IL-17A triggers STAT3 activation in tumor cells, thereby favoring tumor growth." (PMID 27832300, 2017).
tumor (continued). "In this study, STAT3 is found to activate PL2L60-specific promoter, which is associated with increased expression of PL2L60 and, in turn, PL2L60 may stimulate STAT3 gene expression in tumor cells, suggesting that a feedback pathway of STAT3/PL2L60 for promoting tumorigenesis might exist." (PMID 28545024, 2017). "It has been proposed that STAT3 may interact with iron sulfur clusters in the distal region of Complex I to increase its activity and reduce ROS accumulation, which in a murine breast cancer cell model favored cell survival and tumor formation." (PMID 28642839, 2017). "In the current study, we examined EGFR mutant cell lines, including gefitinib-resistant PC9 cell lines, for the effect of afatinib in combination with TPCA-1, in inhibiting tumor growth proliferation and influencing signaling pathways that could down regulate STAT3." (PMID 28521301, 2017). "If regulatory control of SMAD7 is missing at this stage, TGF-β exhibits increased tumor-promotive functions such as epithelial-to-mesenchymal transition, migration and invasion and the activation of tumor-promotive STAT3 signaling could further accelerate the vicious development." (PMID 28134936, 2017). "Panc1 cells exhibit increased p‐Stat3 and p‐Akt expression when treated with conditioned medium from CAFs‐stimulated macrophages, indicating that Stat3/Akt pathway might contribute to the enhanced tumor progression." (PMID 28097809, 2017). "Moreover, we showed that tumor inhibitory effect of GMI was via IL-6/Stat3 signaling pathway." (PMID 29050290, 2017). "In addition, recent reports indicated that IL-17 could induce tumor cells to secrete IL-6 and promote tumor growth by STAT3 pathway." (PMID 28002798, 2017). "Additionally, Stat3 inhibition was responsible for tumor-suppressing role of Shp2." (PMID 28085101, 2017). "Interestingly, in our study, we also observed that the STAT3-blocked HCC vaccine could prevent tumor-induced exhaustion of CD8+ T and NK cells, as depicted by the downregulation of PD-1, TIGIT, and LAG-3 in HCC-vaccine-immunized mice." (PMID 29115974, 2017). "Similarly, the signal transducer and activator of transcription 3 (STAT3), a nuclear transcription factor known for mediating tumor growth, also translocates to the mitochondria where it is necessary for the activity of Complexes I and II and its knockdown impairs OXPHOS." (PMID 28642839, 2017). "Our results imply that the development of inhibitors targeting the mitochondrial activity of Stat3 could be of clinical interest as potential anti-tumor agents and could work either by interference with phosphorylation at S727 or by targeting Stat3 for degradation." (PMID 29133922, 2017). "Pro-inflammatory factors may activate STAT3 in both tumor cells and ECs to induce angiogenesis." (PMID 28978186, 2017). "In addition, icaritin exerted an anti-tumor effect via inhibiting JAKs/STAT3 activation." (PMID 28085115, 2017). "In our previous study, we characterized a mycoplasma-derived highly conserved 240 amino acid small GTPase-like polypeptide (SGLP) that enhances phosphorylation of the signal transducer and activator of transcription 3 (STAT3) by activation of Rac1 and therefore might promote tumor growth." (PMID 28549350, 2017). "However, the lack of IL-17 secretion in patients with the loss-of-function STAT3 mutation due to defective Th17 cell development does not enhance alimentary malignant transformation to induce the tumour-secreting-endocrine RD phenotype." (PMID 28623282, 2017). "Mechanistic study revealed that Hdac7 mutation in mouse lung tumors or HDAC7 depletion in human tumor cell lines resulted in significantly enhanced acetylation and tyrosine-phosphorylation of Stat3 and HDAC7 protein directly interacted with and deacetylateed STAT3." (PMID 29126425, 2017).